AR (androgen receptor)
Diseases named in the same sentence as AR in open-access papers (continued):
Sharing a sentence is not in itself a finding about the gene and the disease.
cancer (continued). "While the AR signaling axis is largely conserved in CRPC — mainly due to various adaptive mechanisms within the cancer cell that preserve the AR transcriptional program despite low availability of androgens — resistance to ARSI is often marked by loss of AR and independence from its signaling axis." (PMID 36212399, 2022). "The role of FOXA1 in AR signalling appears to change during cancer development and progression." (PMID 37435460, 2022). "Positivity of ER, PR and AR was defined as ≥1% of cancer cells showing positive nuclear staining." (PMID 36232774, 2022). "An inverse correlation was also noted between AR and PR (p<0.01) in carcinoma cases." (PMID 35814372, 2022). "However, that same study noted a significant inverse correlation between AR and ERα (p<0.01) in carcinoma." (PMID 35814372, 2022). "In addition, PCAL7 lncRNA is another lncRNA that enhances progression of this type of cancer through promoting AR signaling." (PMID 34831421, 2021). "PDGFR-β and AR inhibition have been considered as approaches for cancer therapy." (PMID 34659545, 2021). "Moreover, despite the concentration of androgen maintained at the level of castration, cancer cells increase with the continuous transcriptional activity of the AR." (PMID 34298646, 2021). "Hence, the distinct ING isoforms need to be identified, functionally investigated separately, and analysed in the context of a specific cancer type as they were frequently shown to have a tissue-specific function, such as AR coregulator activity in PC." (PMID 34685579, 2021). "Based on previous studies showing that CDK1 can specifically phosphorylate AR at serine 81 to activate AR transcriptional activity, we hypothesize that the pro-cancer effect of ABCC5 is mediated by stabilizing CDK1 to activate AR phosphorylation." (PMID 33994848, 2021). "BET inhibitors could be an alternative strategy for targeting AR-driven cancers due to the interaction between the BET family proteins and AR." (PMID 35011350, 2021). "And anti-cancer action is achieved through regulating androgen receptor signaling." (PMID 34311656, 2021). "Among the mechanisms of resistance are the arising mutations in the AR that make the receptor promiscuously activated by drugs or non-specific ligands, thus promoting cancer progression." (PMID 34208290, 2021). "Potential mechanism of the drug effects appear to be at least partly mediated through inhibition of cancer stem cell via AR in gliomagenesis and may provide us with a novel target for GBM treatment." (PMID 34094902, 2021). "Here, we explore some of the top ranked TRs including histone deacetylase 2 (HDAC2), estrogen receptor 1 (ESR1), TEA domain family member 4 (TEAD4), achaete-scute homolog 1 (ASCL1), androgen receptor (AR) and yes associated protein 1 (YAP1) in several cancer types." (PMID 33778495, 2021). "The oncogenic potential of variant, AR-V7 was further demonstrated by a study showing that combined AR-FL and AR-V7 degradation by inhibitors of a de-ubiquitinase, USP7, reduced the proliferative activity of PCa cells, thus advocating the role of AR-Vs in cancer progression." (PMID 33993099, 2021). "Furthermore, other markers of cancer progression and resistance were suppressed, namely VEGF, the androgen receptor, and Androgen Receptor Splice Variant 7, while cytotoxicity increased through a greater number of M1 cytotoxic macrophages." (PMID 33513777, 2021). "For normal prostate tissue, single-cell analysis precisely defined epithelial-expressed genes and confirmed the existence of luminal, basal, or bipotential progenitor populations with specific anatomical locations and potential relevance to cancer characteristics such as AR independence." (PMID 33903734, 2021). "The effects of lncRNAs on AR signaling have also been assessed in other types of cancers." (PMID 34831421, 2021).
cancer (continued). "The key roles of Srcs in AR transcriptional activity, cell proliferation, migration, and resistance to androgen deprivation therapy in cancer indicate that Srcs may be important therapeutic targets." (PMID 34307888, 2021). "In combination, these findings point to a previously unappreciated role AR has on PD-L1 expression in multiple tissue types and, given that the PD-1/PD-L1 axis is an actionable immunotherapeutic target for various cancers, indicate that AR activity can impact the response to immunotherapy." (PMID 34422798, 2021). "These feedback connections between miR-21, the AR, and PTEN suggest that high plasma levels of miR-21 might be an indicator of increased AR activity in cancer cells, which is predictive of response to ARTA." (PMID 33796462, 2021). "Interestingly, based on Higgins renal microarray dataset and the cancer genome atlas (TCGA) DNA copy number data, we found both AR mRNA and genomic DNA content increased in ccRCC." (PMID 33510354, 2021). "The availability of a specific inhibitor of the AR/FlnA complex acting downstream of hormone binding could provide a second line option to repress the metastatic potential of hormone refractory cancers bearing constitutively active AR." (PMID 35011576, 2021). "Similarly, by analyzing the cBio cancer genomics portal data base, we found that the frequency of AR mutants can vary between patient cohorts and can reach up to 15% in metastatic CRPC." (PMID 34208290, 2021). "DDX5 plays a proliferative or oncogenic role in cancer through the coactivation of Androgen Receptor (AR), Runx2 and the p50 subunit of NF-κB, and upregulation of cyclin D1 and c-Myc consistent with β-catenin activation as well as genes necessary for DNA replication." (PMID 33804185, 2021). "Of note, they indicate that PC-derived exosomes are enriched of signaling effectors commonly engaged by the androgen receptor (AR) to transmit its non-genomic effects in PC and stromal cells as well as cancer-associated fibroblasts (CAFs) from PC patients." (PMID 34772427, 2021). "While ADT may be effective against more differentiated AR-positive cells, the reoccurrence of cancer may be due to this subpopulation of AR-independent CSCs." (PMID 33456711, 2021). "Regardless of whether adaption or selection is responsible, approximately one-third of ARSi-resistant cancers are either DNPCs or NEPCs that lack AR expression, and the frequencies of such AR– PCs are increasing." (PMID 33724955, 2021). "ESR1 and AR are the morphogenetic factors that regulate cell proliferation, differentiation, angiogenesis, and the development of some tumors, which were predicted to link the Epimedium to cancer with highest scores." (PMID 33460401, 2021). "Androgen regulated BRDs increased chromatin accessibility by enhancing AR recruitment to chromatin, which may drive cancer progression." (PMID 35011350, 2021). "One of the probable reasons correlating ING expression with PC could be that expression analyses would benefit if data were derived from stratified patient samples analysing a subgroup with low AR and/or more aggressive cancer stage." (PMID 34685579, 2021). "Based on these results, we posited that differential levels of androgen receptor (AR) signaling in SPOP-mutant vs. ERG-fused cancers might be at the root of the incompatibility between the driver events." (PMID 33531470, 2021). "AR is a male hormone receptor and also known as an oncogene of various cancers, including HCC." (PMID 34907204, 2021). "Combination of FAO inhibitors (etomoxir, ranolazine, and perhexiline) with enzalutamide displayed a synergistic inhibitory effect, suggesting that co-targeting FAO and AR may have anti-cancer efficacy in mCRPC clinical setting." (PMID 34386430, 2021). "That this weak association was statistically significant only in the subset of ERG-negative cancers might be first of all related to the strong link between AR and ERG, which might obscure less strong interactions." (PMID 33628598, 2021).
cancer (continued). "Recent insights into the critical role of TME in disease progression underscored the need to investigate how metabolic reprogramming in cancer-associated fibroblasts (CAFs), adipocytes and infiltrating immune cells contributes to disease progression and resistance to ADT/AR signaling inhibitors." (PMID 35582011, 2021). "The increasing degree of AR-positivity in ER- cancers is related to poorer prognosis." (PMID 34638264, 2021). "Androgen receptor impact on neoplastic progress has drawn specific interest, as the significance of testosterone and estrogen axis was recognized in the etiology of all cancer types." (PMID 33920263, 2021). "AR coregulators encompass numerous proteins, with several of particular interest in cancer." (PMID 34638264, 2021). "Other studies have reported highest presence of AR in luminal A cancers and lowest in TNBC." (PMID 34638264, 2021). "Here, we found that PAM could selectively inhibit the proliferation, reduce the migration ability, induce the apoptosis of AR-independent prostate cells and, importantly, through blocking cancer cells at the G0/G1 cell cycle stage." (PMID 34476012, 2021). "Nevertheless, our results showed that AR exhibited a cancer-promoting effect on HCC." (PMID 34907204, 2021). "Importantly, in PCa cells, SRC-2 was reported to interact with AR at the nuclear level to increase the sensitivity of cancer cells to androgens and to enhance the ligand-independent transcription of AR target genes." (PMID 34067217, 2021). "Recently, genome-wide profiling of androgen receptor (AR) negative canine PCa revealed a large number of copy number alterations associated with aberrant expression of cancer-related and tumor suppressor genes." (PMID 34768937, 2021). "Studies in cancer cells have reported significant crosstalk between AR and HIF1α." (PMID 33784295, 2021). "Yet, the cancer remains having high AR expression and dependent on intact AR signaling." (PMID 36046114, 2021). "It is likely that AR affects UBC in complex ways that depend on cancer stage." (PMID 34768683, 2021). "In this study, we developed a series of novel PROTACs to degrade AR in AR-positive cancer cells." (PMID 33926033, 2021). "A notable SNP rs17694493, might decouple AR’s repressive effect on CDKN2B-AS1 and cell cycle regulation, thereby playing a causal role in predisposing cancer risk." (PMID 34513844, 2021). "Let us focus on AR potential as targets to improve the efficacy of anti-cancer immunotherapy." (PMID 34831054, 2021). "The primary cancer is almost always dependent on the AR signaling." (PMID 34137734, 2021). "Moreover, MALAT1 has been shown to suppress cell cycle progression in this type of cancer through regulation of AR signaling." (PMID 34831421, 2021). "Androgen receptor (AR), a target gene of hsa-miR-320a, was enriched in cancer pathways." (PMID 34122072, 2021). "While disease-related AR-driven transcriptional programs are connected to the presence and activity of the receptor itself, also novel modes of transcriptional regulation by androgens are exploited by cancer cells." (PMID 33634124, 2021). "Thus, the BET family can be treated as an alternative strategy for targeting androgen-receptor (AR)-driven cancers." (PMID 35011350, 2021). "Furthermore, studies have shown that the AR-positive SC subtype promotes cancer development through the regulation of the cell cycle by androgen stimulation." (PMID 34299364, 2021). "Overstimulation of the androgen receptor (AR) activity is the main driver of this cancer." (PMID 33993099, 2021). "and (ii) is AR targeting an effective means to enhance anti-cancer chemotherapy?" (PMID 34831054, 2021). "Interestingly, also other SRs have emerged as important 'coregulators' for the ER and AR in cancer cells." (PMID 34137734, 2021).
cancer (continued). "DHX15 play key role in cancer progression through activating AR activity through Siah2-mediated ubiquitination independent of its ATPase activity, but this gene might be liable for development of pituitary prolactinoma." (PMID 33709028, 2021). "Since the unfolding mechanism of AR LLPS may be the key to cancer progression, it is very important to further study the mechanism details of AR LLPS." (PMID 34977151, 2021). "PSA/PAP ratio in advanced cancer may aid in determining which patients would benefit from maximized androgen receptor inhibition or early use of antimicrotubule agents." (PMID 33903734, 2021). "Combining a programmed cell death protein-1 (PD-1) inhibitor (pembrolizumab [PEM]) with a second-generation androgen receptor (AR) antagonist (enzalutamide [ENZ]) at the time of comprehensive therapy for mCRPC has emerged as an option to potentially prolong the progression of cancer and improve OS." (PMID 33849473, 2021). "Over-expression of XIST and AR has been correlated with advanced TNM stage in this cancer." (PMID 34831421, 2021). "Either different DDX3 roles in different types of cancer, oncogenic or suppressive, or the small amount of AR measured MBC patients in this study, could be an explanation for these differences." (PMID 33974127, 2021). "Depending on the type of coregulator, the transcription of the AR target genes and the cancer progression could be affected." (PMID 34743733, 2021). "Previous studies had showed similar function and crosstalk among diverse ARs in TME, which could result in failure of targeting special AR in cancer therapy." (PMID 32205841, 2020). "As mounting evidence points to the regulatory role of AR in cancer cellular senescence, we determined whether SRD5A1 might act as a moderator for CRC cellular senescence." (PMID 32983992, 2020). "Consequently, an abnormal AR expression leads to cancer cell proliferation even in androgen depleted states." (PMID 32867793, 2020). "Similarly, PCa-derived CAFs with decreased expression of AR promote stemness in cancer cells through IFN-γ and M-CSF secretion." (PMID 33553157, 2020). "Moreover, dysregulations of AR activity and expression have been reported in various types of cancer, such as bladder, ovarian, breast and salivary gland cancers." (PMID 31896509, 2020). "Moreover, it has been shown that ADT therapy can select for cancer cells with further increased AR activity, for example, due to AR gene amplification." (PMID 32292603, 2020). "They reported that AR expression is associated with favorable clinicopathologic features and better clinical outcomes in ER-positive cancers, but not in ER-negative cancers." (PMID 32290220, 2020). "Altogether, the combination of ADT and immune therapy could open interesting therapeutic options especially in patients with androgen/AR-dependent cancers." (PMID 32714315, 2020). "Cancer cells have developed multiple ways to escape AR-directed targeting." (PMID 32427840, 2020). "Additionally, Tip60, an important coactivator of the AR, also exhibits instrumental metabolic roles in cancer cells through direct and indirect regulation." (PMID 32927797, 2020). "Interference of different EDCs with ER and AR has been widely screened, but for other receptors such as GR potentially or known to be involved in the development and progression of hormone-related cancer types, further studies are required." (PMID 33287384, 2020). "Furthermore, some previous studies have asserted that AR expression is different in ER-positive and ER-negative cancers and results in different clinical implications." (PMID 32290220, 2020).
cancer (continued). "Using the described STP analysis tests, activity of twelve relevant signaling pathways (PI3K, MAPK, JAK-STAT1/2, JAK-STAT3, NFκB, ER, AR, PR, Notch, TGFβ, Wnt and HH) can be measured simultaneously and quantitatively on individual patient cancer tissue samples from different cancer types." (PMID 33613616, 2020). "Thus, the use of the ARGs expression profile to infer AR activity seems to be an adequate tool to study the role of AR activity in cancer." (PMID 33328560, 2020). "AR siRNA contributed to the anti-cancer effects of brassicasterol in LNCaP cells." (PMID 32972001, 2020). "This overlap suggests that targeting androgens and AR signaling in other cancer types may also be effective." (PMID 33062889, 2020). "Data on hnRNPA1 and AR expression were available from 7157 cancers." (PMID 32417965, 2020). "Altogether, the androgen-independent activation of AR occurs relatively often in cancer." (PMID 32714315, 2020). "Conversely, BPA analogues binding to AR could affect its signalling cascade, which may potentially lead to cancer, as discussed in the following section." (PMID 33287384, 2020). "The binding of androgen to AR initiates the signal of cell growth and proliferation in cancer." (PMID 32972001, 2020). "Androgen signaling pathway is involved in cell growth; based on our observation that CYP3A inhibitors and inducers alter AR nuclear translocation, we hypothesized that they should also alter cancer cell growth." (PMID 32316460, 2020). "This implicates the AR as a major promoter of cancer growth and disease progression." (PMID 33076388, 2020). "We showed that common mouse models of cancer cachexia are refractory to anabolic androgen administration, but, in some cases, anti‐cachectic efficacy can be markedly improved by combined treatment with the HDACi AR‐42." (PMID 31930715, 2020). "The colon‐26 mouse model of cancer cachexia mimics recent late‐stage clinical failures of anabolic anti‐cachexia therapy and was unresponsive to anabolic doses of diverse androgens, including the selective androgen receptor modulator (SARM) GTx‐024." (PMID 31930715, 2020). "It is indicated that Androgen Receptor (AR) could act as an oncoprotein and modulate metastasis and progression of several cancer types 14–16." (PMID 32153739, 2020). "Taken together these results suggest that diminishing IKBKE signalling in PC cells may prove therapeutically beneficial for patients by suppressing AR signalling to prevent cancer cell growth and metastases." (PMID 32324216, 2020). "AR may also be important for promoting the cancer stem cell-like (CSC-like) population in TNBC, in addition to reducing the levels of detachment-induced apoptosis in cells grown in forced suspension compared to attachment conditions." (PMID 33062889, 2020). "Expression of AR in macrophages was established in mice; however, the functionality of AR signalling in macrophages in relation to cancer development remained largely unknown." (PMID 32908142, 2020). "Previous research have extensively reported that AR may play a key role in pancreatic carcinogenesis and cancer development." (PMID 32489450, 2020). "Interestingly, despite both ligands inducing cancer cell senescence, AR agonist and antagonist seem to induce a distinct pro-survival pathway." (PMID 32650419, 2020). "Finally, we investigated the involvement of cellular signaling pathways involved in the anti-cancer effect of AR and/or KDM7A inhibitors on CR-T24 cells." (PMID 32781788, 2020). "Several studies that have explored the potential roles of the AR in these cancer cells indicate that the AR regulates glucose metabolism, including glycolysis, TCA cycle and oxidative phosphorylation (OXPHOS), as well as lipid metabolism in androgen-dependent prostate cancer." (PMID 32927797, 2020). "For the early stage male bladder cancer patients, it would be interesting to explore whether an AR antagonist can be used as an anti-cancer drug upon screening KMD7A expression levels." (PMID 32781788, 2020).